COL1A1 (collagen type I alpha 1 chain)
Diseases named in the same sentence as COL1A1 in open-access papers (continued):
Sharing a sentence is not in itself a finding about the gene and the disease.
left ventricular hypertrophy (1 paper, 2021). Enlargement of the LEFT VENTRICLE of the heart. "miR-133a is decreased in pathological left ventricular hypertrophy, and miR-133a limits the production of CTGF and COL1A1 by directly targeting their 3′-UTR regions." (PMID 34630844, 2021).
low grade glioma (1 paper, 2023). A grade I or grade II glioma arising from the central nervous system. "Research suggested that the expression of COL1A1 was significantly associated with the infiltration level of immune cells, such as CD4 + T cells, CD8 + T cells, dendritic cells and neutrophils in low grade gliomas (LGG)." (PMID 37415178, 2023).
Lowe syndrome (1 paper, 2021). "Moreover, we also showed that HK-2 OCRL KO cells display increased COL1A1 secretion leading to increased extracellular collagen fibre deposition, which may contribute to interstitial fibrosis as observed in Lowe syndrome and Dent II disease patients." (PMID 34069732, 2021).
lumbar disc herniation (1 paper, 2025). "In conclusion, we report a novel case of an 18-year-old male OI patient with multilevel lumbar disc herniation caused by a sporadic COL1A1 mutation." (PMID 40760627, 2025).
lumbar spinal stenosis (1 paper, 2022). A spinal stenosis that involves the lumbar region of vertebral column. "Change of the ratio of Col1a1:Eln has been considered to be a sign of developing lumbar spinal stenosis in elder patients and the COL:ELN ratio was described as an accurate predictor of arterial burst pressure." (PMID 35203717, 2022).
Lymphatic Metastasis (1 paper, 2020). Transfer of a neoplasm from its primary site to lymph nodes or to distant parts of the body by way of the lymphatic system. "We further validate COL1A1 using clinical biopsy samples and demonstrate that COL1A1 expression correlates with lymphatic metastasis and poor clinical outcomes." (PMID 33062455, 2020).
malocclusion (1 paper, 2023). "COL1A1, especially rs2249492, may be a risk gene in class III skeletal malocclusion in Javanese population." (PMID 35672017, 2023).
migraine (1 paper, 2025). "In this study, we identified that NTG-induced migraine is associated with the PI3K–Akt signaling pathway, cytokines and their receptor interactions, and nine key hub genes (Alb, Tgfb1, Cd4, Ptprc, Itgb1, Icam1, Col1a1, Pxdn, and Itgad) through transcriptomics." (PMID 40699640, 2025). "Although current evidence does not directly link Itgb1, Itgad, Col1a1, and Pxdn to migraine, their functional relevance in inflammation and vascular remodeling suggests that they may contribute to migraine pathogenesis." (PMID 40699640, 2025).
multiple epiphyseal dysplasia (1 paper, 2009). Multiple epiphyseal dysplasias (MED/EDMs) are characterized by epiphyseal anomalies causing joint pain early in life, recurrent osteochondritis and early arthrosis. "The genes implicating BMD variation and multiple epiphyseal dysplasias (MED) like COL1A1, COL1A2, CO9A1, COL9A2 and COL9A3 were highly suggestive in humans." (PMID 19284518, 2009).
myxoma (1 paper, 2024). A benign soft tissue neoplasm characterized by the presence of spindle and stellate cells, lobulated growth pattern, and myxoid stroma formation. "Compared with fibroblasts, myxoma cells downregulate the markers of fibroblasts such as COL1A1 and DCN but still retain some abilities of collagen secretion." (PMID 39090109, 2024).
nephrolithiasis (1 paper, 2017). The presence of a calculus in the pelvis of the kidney; this is most often composed of mineral salts and proteins. "Genes encoding for Runx1, Runx2, KRT 18, KRT 8, VIM, Fn-1, Col1a1 and Col1a2 were up regulated during hyperoxaluric conditions and further increased after crystal deposition or nephrolithiasis." (PMID 29091707, 2017).
overactive bladder (1 paper, 2015). Symptom of overactive detrusor muscle of the urinary bladder that contracts with abnormally high frequency and urgency. "These metaanalyses provide moderate epidemiological credibility for associations of variation in ADRB3 with overactive bladder, and variation of COL1A1 with prolapse." (PMID 25111588, 2015). "These metaanalyses provide moderate epidemiological credibility for associations of variation in ADRB3 with overactive bladder, and COL1A1 with prolapse." (PMID 25111588, 2015).
Pancreatic cysts (1 paper, 2012). A cyst of the pancreas that possess a lining of mucous epithelium. "We did not observe renal or pancreatic cysts in heterozygous Col1a1(3.6)-Cre;Pkd1flox/+ mice during embryogenesis or at 6-weeks of age (data not shown)." (PMID 23029375, 2012).
periapical periodontitis (1 paper, 2022). Inflammation of the periapical tissue. "In the periapical periodontitis group, COL1A1 was significantly down-regulated in healing at 6 months (− 28.44) while up-regulated in healing at 12 months group (4.83; p < 0.0001)." (PMID 35970906, 2022).
peripheral T-cell lymphoma (1 paper, 2022). "COL1A1 has previously been reported to be upregulated in peripheral T-cell lymphoma." (PMID 36873459, 2022).
Peyronie disease (1 paper, 2022). A condition characterized by hardening of the penis due to the formation of fibrous plaques on the dorsolateral aspect of the penis, usually involving the membrane (tunica albuginea) surrounding the erectile tissue (corpus cavernosum penis). "Moreover, our results correlate with data obtained from myofibroblasts isolated from other pathological tissues, namely plaque tissue from Peyronie’s disease and forearm skin of patients with diffuse subset scleroderma, where expression of COL1A1 is also decreased after VP treatment." (PMID 35977978, 2022).
pheochromocytoma (1 paper, 2021). "In conclusion, we found that the inactivation of pVHL in pheochromocytoma led to the up-regulation of the seven novel genes, such as CTGF, SDCBP, CYR61, COL3A1, COL1A1, COL5A2, and SERPINE1." (PMID 33828526, 2021).
pneumonitis (1 paper, 2018). An inflammatory process affecting the lung parenchyma. "The lung of BLM group developed pneumonitis with severe cellular infiltrations at 7 days and significant collagen deposition (MT) and higher expression of Col1a1, and Col3a1 at 21 days post-administration." (PMID 29497425, 2018).
prediabetes (1 paper, 2022). "The PBMC-isolated from 25 patients with prediabetes (25/28) expressed ALPL, BGLAP, COL1A1, and RUNX2/PPAR and the PBMC-isolated from 15 patients with normoglycemia (15/17) expressed those genes." (PMID 35237235, 2022).
proliferative diabetic retinopathy (1 paper, 2023). Advanced retinopathy due to diabetes mellitus characterized by the formation of new vessels in the retina. "Moreover, Col1a1 expression was up-regulated in the aqueous humor of the patients with proliferative diabetic retinopathy (PDR) or retinopathy of prematurity (ROP) and up-regulated in the proliferative membranes of PDR patients." (PMID 37215579, 2023).
Pulmonary hemorrhage (1 paper, 2025). Pulmonary hemorrhage is a bleeding within the lungs. "Two novel and two pathogenic mutations in COL3A1 gene associated with vEDS, COL1A1, COL1A2, TNXB gene mutations of non-vascular types underlying EDS and COL4A2 gene associated with collagen synthesis were found in patients presenting with pulmonary hemorrhage." (PMID 40598578, 2025).
pyelonephritis (1 paper, 2020). An inflammatory process affecting the kidney. "In comparison, our pyelonephritis model features regional injury and scarring that is comparatively limited in scope; as a result, analysis of our whole‐kidney homogenates did not reveal increased Col1A1 (collagen I) and Acta2 (α‐smooth muscle actin) transcription in TC‐treated mice." (PMID 32227630, 2020).
rectal cancer (1 paper, 2021). A primary or metastatic malignant neoplasm that affects the rectum. "In rectal cancer, COL1A1 and MZB1, as the key genes of rectal cancer, can interact with other genes correlated with shorter survival for patients." (PMID 33841514, 2021).
Renal atrophy (1 paper, 2021). Atrophy of the kidney. "In a recent paper focusing on a 29-peptide classifier (five of which were col1a1 peptides) to evaluate interstitial fibrosis and renal atrophy in a non-invasive approach, three urinary col1a1 peptides were reported to negatively correlate with interstitial fibrosis and renal atrophy." (PMID 35050988, 2021).
Renal cyst (1 paper, 2012). A fluid filled sac in the kidney. "Pancreatic and renal cysts developed by E15.5, just after highly expression of Col1a1(3.6)-Cre activity in skeletal tissues at E12.5." (PMID 23029375, 2012).
retinal detachment (1 paper, 2016). An eye emergency condition which may lead to blindness if left untreated. "Here, we report on the novel association of compound heterozygous variants in collagen type I alpha 1 gene (COL1A1, OMIM 120150) in one patient diagnosed with PCG and retinal detachment." (PMID 27484908, 2016). "In the patient diagnosed with PCG and retinal detachment, analysis of WES data identified compound heterozygous variants in COL1A1 (p.Met264Leu; p.Ala1083Thr)." (PMID 27484908, 2016).
skin changes (1 paper, 2024). "The gene sets encompass numerous genes previously implicated in the pathogenesis of SSc, such as Acta2, Col1a1, Col3a1, Smad3, Ctgf, Msr1, Cd4, Cd8a and Cd68, supporting the potential of anti-PRMT5 in induction of SSc-like skin changes." (PMID 38684324, 2024).
stress incontinence (1 paper, 2015). "The rs1800012 polymorphism of the COL1A1 gene was associated with prolapse (OR, 1.3; 95% CI, 1.0–1.7; n = 838) and stress urinary incontinence (OR, 2.1; 95% CI, 1.4–3.2; n = 190)." (PMID 25111588, 2015). "The available data on gene and protein expression in pelvic tissue from women with prolapse or stress incontinence are heterogeneous but suggest increased COL1A1 expression with reduced type 1 collagen content." (PMID 25111588, 2015).
teratoma (1 paper, 2025). A non-seminomatous germ cell tumor characterized by the presence of various tissues which correspond to the different germinal layers (endoderm, mesoderm, and ectoderm). "Nes-GFP+ pNSCs were similar to brain NSCs in self-renewal, lack of teratoma formation, marker gene expression, genome-wide gene expression pattern and DNA methylation pattern on Nestin and Col1a1 loci." (PMID 40211073, 2025).
ulcerative colitis (1 paper, 2025). An inflammatory bowel disease involving the mucosal surface of the large intestine and rectum. "In conclusion, we identified a close association between COL1A1, LOXL2, VWF, MZB1, and ERS in the pathogenesis of ulcerative colitis (UC)." (PMID 40607383, 2025). "Through this approach, we demonstrated that COL1A1, LOXL2, and VWF may participate in the fibrotic pathological process of ulcerative colitis by regulating fibrosis-related pathways." (PMID 40607383, 2025).
Vestibular schwannoma (1 paper, 2025). A vestibular schwannoma (also known as acoustic neuroma, acoustic neurinoma, or acoustic neurilemoma) is a benign, usually slow-growing tumor that develops from the VIIIth cranial nerve supplying the inner ear. "Collagen, COL1A1 and COL3A1, were also overrepresented in our analysis and recently shown to be associated with recurrence of vestibular schwannoma after radiation therapy." (PMID 40585242, 2025).
vitamin D deficiency (1 paper, 2016). A nutritional condition produced by a deficiency of VITAMIN D in the diet, insufficient production of vitamin D in the skin, inadequate absorption of vitamin D from the diet, or abnormal conversion of vitamin D to its bioactive metabolites. "It was interesting to note that differences in COL1A1 were only evident at the P7 time-point from the LC-MS/MS assay, whereas the ELISA analysis showed that vitamin D deficiency increased the expression of COL1A1 at E14.5, E17.5 and P7." (PMID 27121020, 2016). "In our study, COL1A1 was increased in lungs of vitamin D deficient mice suggesting that collagen synthesis during lung development is also sensitive to vitamin D. Again, this is consistent with the functional defects associated with maternal vitamin D deficiency that have been described previously." (PMID 27121020, 2016). "Importantly, SP-B and COL1A1 have biologically plausible associations with lung structure and function, which are consistent with the postnatal lung function changes associated with maternal vitamin D deficiency." (PMID 27121020, 2016).
tumor (506 papers, 2005 to 2026). "Whereas the TME of primary and recurrent AGCTs are frequently similar in many respects, distinct AGCT TME subtypes exist that are defined by the close association between FOXL2+ tumor cells and local COL1A1." (PMID 41042551, 2025). "The MCS exhibited improved viability and a gene expression profile associated with aggressive tumor characteristics, including increased expression of genes linked to cell survival and motility, such as COL1A1, MSN, HIF1A, TUBB, and ACTB." (PMID 41516217, 2025). "In cancers such as breast and pancreatic cancer, COL1A1 overexpression has been associated with a desmoplastic reaction that fosters tumor growth and hampers immune responses." (PMID 40817072, 2025). "Intercellular crosstalk analyses using CellChat and tissue staining implicated the ANGPTL4–SDC4 axis in interactions between COL1A1+ ECs and tumor cells." (PMID 41154806, 2025). "COL1A1, encoding collagen type I alpha 1, has been shown to play a critical role in tumor progression." (PMID 38347596, 2024). "Collagen type I alpha 1 chain (COL1A1) is a key protein encoding fibrillar collagen, playing a crucial role in the tumor microenvironment (TME) due to its complex functions and close association with tumor invasiveness." (PMID 39845977, 2024). "In the tumor microenvironment, cancer-associated fibroblasts (CAFs) play a key role in reorganizing and cross-linking COL1A1, leading to its accumulation and the stiffening of the stroma." (PMID 39850811, 2024). "While in tumor subgroups with decreased mesenchymal stem cells, low COL1A1 expression was associated with a better prognosis in OC (HR=0.66, p=0.023)." (PMID 39845977, 2024). "Depending on the type of tumor, myCAF-expressed COL1A1 has been linked to both tumor-promoting and tumor-restraining activities." (PMID 39766138, 2024). "These secondary analysis results of external scRNA-seq data further confirm that these COL1A1+/COL1A2+/IGFBP2+ fibroblast-like cells are tumor associated and play a central role in the TME of brain metastasis tissues." (PMID 37479733, 2023). "Subcluster mFibro accounted for the majority of the fibroblast populations in tumor tissue and expressed a high level of COL1A1, MMP11, FN1 and POSTN, which were associated with collagen secretion and extracellular matrix modeling." (PMID 37265785, 2023). "There was a trend towards upregulation of genes encoding fibroblast activation markers (Col1a1, Mrc2, Acta2) in the presence of tumor-infiltrating CD8+ T cells." (PMID 38259467, 2023). "Consistent with the expectation, the expression of COL1A1 and BGLAP was higher in tumor tissues than in normal tissues, and high expression of COL1A1 and BGLAP was associated with higher GS and BCR rate (P < 0.01)." (PMID 37564213, 2023). "Collagen type I alpha 1 (COL1A1) is perhaps the most strongly associated with the development of metastases in cancer as a critical element of the tumor microenvironment." (PMID 36980717, 2023). "Collagen type I alpha 1 (COL1A1), as an important component of tumor microenvironment, encodes the precursor α1 chain of type I collagen (COL I), which forms a triple helix composed of two α1 chains and one α2 chain." (PMID 38045487, 2023). "Intriguingly, according to our study and previous literature, almost all of the USP6-associated neoplasms with bone metaplasia adopt COL1A1 as the fusion partner, including MO, FOPD, ST-ABC and FO." (PMID 36727055, 2022). "Here, the authors characterize dynamic anatomical structures in HGG called oncostreams, which are associated with tumor growth and are regulated by COL1A1." (PMID 35750880, 2022).